ELF3 (E74 like ETS transcription factor 3)
Description:
Transcriptional activator that binds and transactivates ETS sequences containing the consensus nucleotide core sequence GGA[AT]. Acts synergistically with POU2F3 to transactivate the SPRR2A promoter and with RUNX1 to transactivate the ANGPT1 promoter. Also transactivates collagenase, CCL20, CLND7, FLG, KRT8, NOS2, PTGS2, SPRR2B, TGFBR2 and TGM3 promoters. Represses KRT4 promoter activity. Involved in mediating vascular inflammation. May play an important role in epithelial cell differentiation and tumorigenesis. May be a critical downstream effector of the ERBB2 signaling pathway. May be associated with mammary gland development and involution. Plays an important role in the regulation of transcription with TATA-less promoters in preimplantation embryos, which is essential in preimplantation development (By similarity).
Synonyms: ESE-1; ERT; ESX; EPR-1
Tractability: Small molecule: a high-quality ligand is known. PROTAC: ubiquitination databases record sites on it; a small molecule that binds it is known.
Gene: Protein-coding gene on chromosome 1 (202,007,945 to 202,017,183, forward strand). Ensembl gene ENSG00000163435.
Subcellular location: Cytoplasm; Nucleus
Subcellular location (Human Protein Atlas): Nucleoplasm
Pathways (Reactome):
Signal Transduction: Pre-NOTCH Transcription and Translation
Gene Ontology:
Molecular function: DNA-binding transcription activator activity, RNA polymerase II-specific; protein binding; sequence-specific double-stranded DNA binding; DNA-binding transcription factor activity; DNA-binding transcription factor activity, RNA polymerase II-specific; DNA binding; RNA polymerase II cis-regulatory region sequence-specific DNA binding; sequence-specific DNA binding
Biological process: inflammatory response; negative regulation of DNA-templated transcription; positive regulation of transcription by RNA polymerase II; cell differentiation; mammary gland involution; regulation of transcription by RNA polymerase II; regulation of DNA-templated transcription
Cellular component: cytoplasm; nucleoplasm; nucleus; chromatin
Genetic constraint (gnomAD): Loss-of-function variants: 21 observed, 44.62 expected, observed/expected ratio (o/e) 0.47, 90% interval 0.33 to 0.68. The upper end of that interval is the gene's LOEUF score, 0.68, which puts it in group 2 of 6, group 1 being the genes least tolerant of losing a copy. Missense variants: 373 observed, 495.79 expected, observed/expected ratio (o/e) 0.75, 90% interval 0.69 to 0.82. Synonymous variants: 181 observed, 194.08 expected, observed/expected ratio (o/e) 0.93, 90% interval 0.82 to 1.05.
Homologues: Orthologues: macaque ELF3 (97% identical), chimpanzee ELF3 (96% identical), rabbit ELF3 (90% identical), guinea pig ELF3 (88% identical), rat Elf3 (88% identical), mouse Elf3 (87% identical), pig ELF3 (84% identical), tropical clawed frog elf3 (50% identical), zebrafish elf3 (44% identical). Paralogues in human: EHF (32% identical), ELF5 (23% identical), ETS1 (20% identical), ETS2 (19% identical), ELF4 (18% identical), ELF2 (18% identical), ERG (18% identical), FLI1 (18% identical), ELF1 (17% identical), ETV6 (17% identical), GABPA (17% identical), ETV4 (16% identical), and 16 more.
Diseases named in the same sentence as ELF3 in open-access papers:
ELF3 is named in the same sentence as 127 diseases in open-access papers, as found by Europe PMC text mining. Sharing a sentence is not in itself a finding about the gene and the disease. The quoted sentences say what the papers report.
breast cancer (32 papers, 2009 to 2026). A primary or metastatic malignant neoplasm involving the breast. "(B) T-distributed statistical neighbor embedding (t-SNE) plots visualizing the replication stress scores and ELF3 expression levels in breast cancer and normal mammary tissue from a BRCA1-mutated triple-negative breast cancer patient." (PMID 41498327, 2026). "Since most BRCA1 mutation carriers develop basal-like breast cancers, we next investigated the association between ELF3 and basal-like breast cancers." (PMID 41498327, 2026). "Analysis of publicly available breast cancer patient data showed that high ELF3 expression was associated with poor prognosis and enrichment in programs associated with cell cycle progression." (PMID 39905117, 2025). "Analysis of the METABRIC breast cancer cohort revealed that high expression of ELF3 was associated with worse outcome and higher cell-cycle related pathway activity." (PMID 39905117, 2025). "Other studies have directly implicated Elf-3 in the normal physiology of the breast, as well as in breast cancer." (PMID 34072506, 2021). "In this study, we identified an EHF mutation that lies in the ESE domain (L285P) in breast cancer cells, which corresponds to the L329P mutation in ELF3 in bladder carcinoma." (PMID 33712555, 2021). "Our study reveals why BRCA1 deficiency is prone to result in tumorigenesis in LPs and elucidates the key role of replication stress and ELF3 during this process, suggesting that ELF3 could be a promising target for BRCA1-associated breast cancers." (PMID 41498327, 2026). "ELF3 is upregulated in BRCA1-associated breast cancers and is related to a worse prognosis." (PMID 41498327, 2026). "However, the mechanism of high ELF3 expression in certain types of breast cancer and its association with breast cancers beyond the Her2+ subtype is currently unknown." (PMID 41498327, 2026). "Thus, we wondered whether the high expression levels of ELF3 in BRCA1-associated breast cancers are due to copy number variation." (PMID 41498327, 2026). "The association of ELF3 with this epithelial phenotype that also exhibits a more resistant phenotype may be one of the key contributing factors that explain the relationship between ELF3 and worse survival in breast cancer." (PMID 36864480, 2023). "(C) ELF3 expression levels of different molecular subtypes of breast cancers in the TCGA and METABRIC databases (one-way ANOVA)." (PMID 41498327, 2026). "Functional studies were performed using ELF3 knockdown in breast cancer cell lines, followed by WST-1 assays and crystal violet staining." (PMID 42198413, 2026). "(F) ELF3 expression levels of the indicated types of human breast cancers (Mann-Whitney U test, *p<0.05)." (PMID 41498327, 2026). "In the BRCA1-deficient breast cancer cell line HCC1937, knockdown of ELF3 resulted in a significant increase in spontaneous γH2AX foci, demonstrating that ELF3 deficiency leads to more endogenous DNA damage in BRCA1-deficient breast cancer cells." (PMID 41498327, 2026). "During cancer progression, BRCA1 mutant cancer cells gradually become reliant on high ELF3 expression to preserve a certain degree of genomic stability, making ELF3 a promising therapeutic target and biomarker in BRCA1-associated breast cancers." (PMID 41498327, 2026). "HSP27 was identified as a binding partner that stabilizes ELF3 protein, thereby promoting breast cancer cell proliferation." (PMID 42198413, 2026). "As we expected, ELF3 showed the highest expression levels in basal-like breast cancer in both databases." (PMID 41498327, 2026). "We next explored the expression of ELF3 in breast cancers in the TCGA and METABRIC databases to further investigate the association between ELF3 and BRCA1 and validate our previous analysis." (PMID 41498327, 2026). "We exploited the TCGA and METABRIC databases to compare ELF3 expression levels among different breast cancer subtypes." (PMID 41498327, 2026).
breast cancer (continued). "Our study reveals why BRCA1 deficiency is prone to result in tumorigenesis in LPs and elucidates the key role of replication stress and ELF3 during this process and suggests promising targets for BRCA1-associated breast cancers." (PMID 41498327, 2026). "In breast cancers, ELF3 shows high expression, plays an oncogenic role by promoting EMT and forms a positive feedback loop with Her2 to maintain the transformation phenotype of Her2+ breast cancers." (PMID 41498327, 2026). "ELF3 expression is significantly increased in lung cancer patients compared to the normal control group, as well as in other types of cancer (e.g., breast cancer, cervical squamous cell carcinoma, and endocervical adenocarcinoma, stomach adenocarcinoma)." (PMID 39695109, 2024). "We observed that in a majority of cancer types, including breast cancer, prostate cancer and bladder cancer, ELF3 correlated positively with epithelial scores and negatively with mesenchymal scores." (PMID 36864480, 2023). "Conversely, among 25 breast cancer datasets where ELF3 correlated significantly with the mesenchymal signature, the correlation was negative in 20 datasets." (PMID 36864480, 2023). "ELF3 directly binds key labor program-driving ER alpha (ERɑ) and represses ERɑ-mediated gene transcription in breast cancer cells; ELF3 has also been shown to decrease activation of labor-associated collagen genes in a non-SMC context." (PMID 36595497, 2023). "In line with this, several potential tumor-suppressive genes including HOXA5 and ELF3 have been shown to be upregulated by retinoids in breast cancer cells." (PMID 36497371, 2022). "The human ELF3 gene displays a notable upregulation in human malignancies, associated with poor survival outcomes in HER2+ breast cancer patients and poor diagnosis in patients with papillary thyroid cancer." (PMID 34072506, 2021). "Recently, we found that ELF3 is highly expressed in the luminal subtype of breast cancer cells, and represses upregulation of ZEB1/2 by ETS1 in such cells." (PMID 33712555, 2021). "ELF3 directly binds Estrogen Receptor α (ERα) and it represses its transcriptional activity in ERα positive breast cancer, showing a tumour suppressive role." (PMID 31200542, 2019). "HER2+ breast cancers with high ELF3 mRNA expression have a worse outcome, and ELF3 knockdown in HER2+ breast cancer cell lines attenuated tumour growth through inhibition of AKT signaling." (PMID 30200227, 2018). "In Estrogen Receptor α (ERα) positive breast cancer, ELF3 directly binds and represses the transcriptional activity of ERα, suggestive of a tumour suppressive role." (PMID 30200227, 2018). "Our data set derived from invaded breast cancer cells also revealed a significant downregulation of E74-like factor 3 (ELF3)." (PMID 25593984, 2014). "Second, the higher replication stress levels in LPs may lead to altered expression or modifications of molecules other than ELF3, affecting the development and progression of BRCA1-associated breast cancer, which also needs to be further explored." (PMID 41498327, 2026). "ELF3 shows significant copy number amplification in breast cancer." (PMID 41498327, 2026). "The higher levels of ELF3 expression in Her2 subtype breast cancer are consistent with previous studies showing that ELF3 may be a downstream transcription target of Her2 and that there might be a positive feedback loop between them." (PMID 41498327, 2026). "Additionally, TNBCs have higher ELF3 expression levels than the Her2 subtype, revealing a tighter connection between ELF3 and BRCA1-associated breast cancers." (PMID 41498327, 2026). "Furthermore, among human breast cancer tissue samples, ELF3 expression levels were significantly higher in TNBCs than in other subtypes." (PMID 41498327, 2026). "We next asked whether ELF3 expression levels were related to recurrence free survival in breast cancer patients, with the hypothesis that patients with high ELF3 expression would have worse survival." (PMID 39905117, 2025).
breast cancer (continued). "Motivated by these ELF3 observations, we hypothesized that ELF3 expression may be predictive of overall survival in breast cancer." (PMID 39905117, 2025). "To that end we assessed the METABRIC50 breast cancer cohort, using ELF3 expression to stratify patients into three categories: ‘high’ (Upper quartile of ELF3 expression), ‘mid’ (Inter quartile range of ELF3 expression), and ‘low’ (Lower quartile of ELF3 expression)." (PMID 39905117, 2025). "Finally, in meta-analysis across multiple transcriptomic datasets belonging to breast cancer, ovarian cancer and bladder cancer, we investigated the correlation of ELF3, GRHL2 and KLF4 with epithelial and mesenchymal gene sets." (PMID 36864480, 2023). "ELF3 was initially found to be overexpressed in HER2 positive breast cancer." (PMID 33144684, 2021). "So far, it remains unclear how ELF3 inhibits ZEB1 promoter activation by ETS1 in breast cancer cells." (PMID 33712555, 2021). "ELF3 knockdown also inhibited the growth in HER2+ trastuzumab-resistant breast cancer cell lines." (PMID 30200227, 2018). "Studies in breast cancer suggest ELF3 may function as either a tumour promoter or suppressor, depending on the molecular subtype of the disease." (PMID 30200227, 2018). "Furthermore, we investigated whether ELF3 expression could be a biomarker for breast cancer prognosis." (PMID 41498327, 2026). "Therefore, we speculated that ELF3 could be an important driving factor during the tumorigenesis of BRCA1-deficient and basal-like breast cancer." (PMID 41498327, 2026). "Based on the association between ELF3 and the worse prognosis in BRCA1-associated breast cancer patients, we hypothesized that upregulation of ELF3 could help cells deal with replication stress and suppress excessive genomic instability, facilitating cancer initiation and cancer evolution." (PMID 41498327, 2026). "Thus, in breast cancer, higher ELF3 or lower WT1 levels associated with worse outcomes, while in colorectal and ovarian cancer, lower ELF3 or higher WT1 levels had worse prognosis, reminiscent of the antagonistic role of ELF3 and WT1 in mediating phenotypic plasticity." (PMID 36864480, 2023). "Finally, two genes are associated with non-prostatic neoplasms: ELF3 with breast cancer and COL6A1 with astrocytoma." (PMID 20500816, 2010). "We found that higher ELF3 expression is correlated with worse prognosis in TNBC and basal-like breast cancer." (PMID 41498327, 2026). "Furthermore, ELF3 knockdown in HCC1937 and SUM149PT cells, both of which are human breast cancer cell lines with BRCA1 mutations and allelic loss, also caused a significant decline in cell proliferation, suggesting that ELF3 is essential for BRCA1 mutant breast cancer cell survival." (PMID 41498327, 2026). "ELF3 has been reported to be involved in functions, including EMT in human breast cancer and promotes the transformation of normal human mammary cells." (PMID 41498327, 2026). "ELF3, in turn, can repress upregulation of ZEB1/2 by ETS1 in breast cancer, head and neck squamous carcinoma and in normal bile duct epithelial cells." (PMID 36864480, 2023). "As a result of our algorithm, we identified a signature of 5 CTC-specific genes, i.e., ADPRHL1, ELF3, FCF1, TFF1 and TFF3, and explored its clinical significance according to their expression in CTC-enriched blood samples in our breast cancer case series." (PMID 35216615, 2022). "To examine the relationship between RAR and ERK signaling in breast cancer cells, we first verified that expression of potential tumor-suppressive genes, HOXA5 and ELF3, was induced by RA treatment in an RAR-dependent manner in MCF7 breast cancer cells." (PMID 36497371, 2022). "Stabilisation of ELF3 by PAK1 promoted ERK signalling and anchorage-independent growth in breast cancer cells." (PMID 34066106, 2021). "(B) Correlation of ELF3 and BRCA1 expression levels in TCGA breast cancer datasets." (PMID 41498327, 2026).
breast cancer (continued). "In TCGA basal-like breast cancer, the ELF3 amplification proportion was not higher than that in other subtypes but was only 3.5%, which was lower than the total level (7.3%)." (PMID 41498327, 2026). "Interestingly, ELF3 expression shows less or no prognostic prediction value in luminal A and luminal B subtypes, suggesting that ELF3 plays a more powerful role in TNBC and basal-like breast cancer." (PMID 41498327, 2026). "(A) ELF3 expression levels in BRCA1-associated breast cancers and BRCA1-non-associated breast cancers in the TCGA and METABRIC databases." (PMID 41498327, 2026). "Based on these findings, they developed a synthetic 17 aa ELF3 peptide of this region which inhibited the DNA binding activity of ERα and proliferation of ERα positive but not ERα negative breast cancer cell lines." (PMID 30200227, 2018). "Elevated levels of the ELF3 protein have been detected in some but not all breast cancer cell lines." (PMID 23460839, 2013). "In the main part of this study, the expression of the panel of 5 RT-PCR markers (TACSTD1, EPHB4, ELF3, EGFR, and MGB1) was determined after immunobead enrichment of circulating epithelial cells in blood samples obtained from 56 early stage breast cancer patients." (PMID 19500345, 2009). "Immunomagnetic enrichment of circulating tumour cells followed by RT-PCR (immunobead RT-PCR) with a panel of five epithelial specific markers (ELF3, EPHB4, EGFR, MGB1 and TACSTD1) was used to screen for circulating tumour cells in the peripheral blood of 56 breast cancer patients." (PMID 19500345, 2009). "Our current model is able to explain survival trends in breast cancer, but not in colorectal cancer, thus highlighting different possible coupling of ELF3 with EMT and/or other axes of plasticity, and the interplay of these axes of plasticity in determining patient outcome." (PMID 36864480, 2023). "It was also demonstrated that the nuclear localization of Elf-3 protein induces apoptosis in non-transformed mammary epithelial cells via a transcription-dependent mechanism, giving Elf-3 an additional cellular function and strengthening its potential oncogenic role in human breast cancer." (PMID 34072506, 2021).